UBAP2L (ubiquitin associated protein 2 like)
Diseases named in the same sentence as UBAP2L in open-access papers (continued):
Sharing a sentence is not in itself a finding about the gene and the disease.
glioma (3 papers, 2017 to 2023). A benign or malignant brain and spinal cord tumor that arises from glial cells (astrocytes, oligodendrocytes, ependymal cells). "UBAP2L is a critical factor for hematopoietic stem cell activity and exhibits critical functions in glioma cell growth." (PMID 29287594, 2017).
cognitive deficits (2 papers, 2022 to 2024). "Ubap2l haploinsufficiency in mouse led to social and cognitive impairments accompanied by disrupted neurogenesis and reduced SG formation during early brain development." (PMID 35977029, 2022). "Our Ubap2l haploinsufficiency mouse model shows moderate DD and behavioral defects, including social deficits and cognitive impairments, which mimic the phenotypes observed in patients." (PMID 35977029, 2022). "Ubap2l haploinsufficiency in mouse leads to social disability and cognitive impairments, which resemble the symptoms that we observed in individuals with UBAP2L LGD variants." (PMID 35977029, 2022). "Furthermore, heterozygous defective mice exhibited diminished preference for social novelty, cognitive deficits, and anxiety-like behavior, indicating a role for UBAP2L dysfunction in the neurodevelopmental deficits observed in affected individuals." (PMID 39720179, 2024).
gastric tumor (2 papers, 2021 to 2024). "The anti-gastric tumor effect of miR-148b-3p is possibly related to UBAP2L downregulation." (PMID 34823423, 2021).
lung cancer (2 papers, 2022). A malignant neoplasm involving the lung. "Our results, together with previous reports demonstrated UBAP2L was potential crucial regulator of NSCLC.At present, tissue typing alone can no longer meet the needs of individualized treatment of lung cancer." (PMID 35433677, 2022).
acute respiratory failure (1 paper, 2022). Life-threatening respiratory failure that develops rapidly. "Of note, UBAP2L KO mice die before birth or within minutes after surgical delivery from acute respiratory failure, demonstrating that UBAP2L holds housekeeping functions, essential for living organisms." (PMID 35794863, 2022).
autism (1 paper, 2022). Persistent deficits in social interaction and communication and interaction as well as a markedly restricted repertoire of activity and interest as well as repetitive patterns of behavior. "UPF3B- and UPF2-related disorders recapitulate many of the phenotypes observed in patients carrying the UBAP2L variant, including mild to severe ID, autism-like behaviors, and seizures." (PMID 35977029, 2022).
Azoospermia (1 paper, 2020). Absence of any measurable level of sperm,whereby spermatozoa cannot be observed even after centrifugation of the semen pellet. "The result indicated that reduced UBAP2L expression or assembly in the testis was positively associated with azoospermia." (PMID 31114027, 2020). "As germ cells are also rich in RNA granules, we examined the possible correlation between aberrant expression of UBAP2L and spermatogenic defects in patients with azoospermia." (PMID 31114027, 2020).
clear cell renal cell carcinoma (1 paper, 2025). "Our findings suggest that targeting the O-GlcNAcylation of UBAP2L represents a novel therapeutic strategy for treating clear cell renal cell carcinoma." (PMID 41029457, 2025).
COVID-19 (1 paper, 2022). A disease caused by infection with severe acute respiratory syndrome coronavirus 2. "Our analysis highlighted three COVID-related CpGs annotated to genes PM20D1 and UBAP2L that were putatively causal for COVID-19 severity; more research is needed to understand if and how these CpGs might influence outcome in patients with the COVID-19." (PMID 36380121, 2022).
endometrial cancer (1 paper, 2024). Primary or metastatic malignant neoplasm involving the endometrium (mucous membrane that lines the endometrial cavity). "Concerning SdhA and UBAP2L, their involvement in the regulation of stemness-associated markers must be explored in endometrial cancer, which may reveal potential therapeutic targets." (PMID 38893151, 2024). "Proteomic analysis revealed 105 common proteins altered in ECC-1 and RL95-2 cells upon DEAB treatment, suggesting ALDH18A1, SdhA, and UBAP2L as potential markers for endometrial cancer." (PMID 38893151, 2024). "Furthermore, ALDH18A1, SdhA, and UBAP2L should be explored as novel molecular targets for endometrial cancer." (PMID 38893151, 2024). "Additionally, DEAB modulates the expression of certain proteins, namely, ALDH18A1, SdhA, and UBAP2L, identified in endometrial cancer, which might be promising prognostic and therapeutic targets." (PMID 38893151, 2024). "Moreover, it was possible to identify three proteins as potential biomarkers for endometrial cancer, namely, ALDH18A1, SdhA, and UBAP2L." (PMID 38893151, 2024).
Infertility (1 paper, 2013). "Ubap2l is associated with proteasome mediated protein degradation and has been implicated in infertility." (PMID 24454361, 2013).
language disorder (1 paper, 2024). A category of disorders characterized by an impairment in the development of an individual's language capabilities, which is in contrast to his/her non-verbal intellect. "The speech domain appeared particularly vulnerable, with all patients (13/13) showing speech delays, and about half of them exhibiting marked delays, suggesting that language disorders are a typical symptom of UBAP2L deficiency syndrome." (PMID 39720179, 2024).
malignant glioma (1 paper, 2018). A grade III or grade IV glioma arising from the central nervous system. "Knockdown of UBAP2L led to reduced growth of the malignant glioma and correlated with blockage of G0/G1 cell cycle progression." (PMID 29196913, 2018).
metastatic tumour (1 paper, 2016). "Six genes were associated with tumour pathologic PT and tumour stage; among these, high expression of INTS8 and UBAP2L, and low expression of ACSM3, FCN2, LCAT, and MT1G, was significantly associated with metastatic tumour and late stage (P ≤ 0.05)." (PMID 27567667, 2016).
neuroblastoma (1 paper, 2013). Neuroblastoma (NB) is the most common solid, extracranial childhood tumor. "UBAP2L has been reported to accumulate at ubiquitin-rich aggregates upon proteasome inhibition in human neuroblastoma tissue culture cells, suggesting that the UBA domain is functional." (PMID 23874212, 2013).
non-small cell lung carcinoma (1 paper, 2022). A group of at least three distinct histological types of lung cancer, including non-small cell squamous cell carcinoma, adenocarcinoma, and large cell carcinoma. "First, in non-small cell lung cancer (NSCLC), miR-19a-3p directly inhibits UBAP2L, resulting in similar phenotypes as those observed upon UBAP2L downregulation, mainly inhibition of cell proliferation, migration and invasion." (PMID 35794863, 2022).
renal cell carcinoma (1 paper, 2025). "Together, these data indicate that OGT-mediated O-GlcNAcylation of UBAP2L at serine 305 regulates stress granule formation and sunitinib resistance in renal cell carcinoma." (PMID 41029457, 2025). "Herein, we constructed the acquired sunitinib-resistant ccRCC PDX model and cell models and demonstrated that UBAP2L regulates sunitinib resistance in renal cell carcinoma by modulating stress granule assembly." (PMID 41029457, 2025).
triple-negative breast carcinoma (1 paper, 2023). An invasive breast carcinoma which is negative for expression of estrogen receptor (ER), progesterone receptor (PR), and human epidermal growth factor receptor 2 (HER2). "Additionally, our recent work has revealed UBAP2L as a vulnerability in Myc-amplified triple-negative breast cancer cells." (PMID 37673892, 2023).
viral infections (1 paper, 2024). "Furthermore, UBAP2L is implicated in the formation of stress granules (SGs), which are essential for cell survival under stress conditions and have been linked to the pathogenesis of cancer, neurodegeneration, inflammatory diseases, and viral infections." (PMID 39720179, 2024).
cancer (13 papers, 2018 to 2025). A tumor composed of atypical neoplastic, often pleomorphic cells that invade other tissues. "Recent studies have confirmed that UBAP2L functions as an oncogene and is associated with various types of cancer." (PMID 35406724, 2022). "UBAP2L enables P65 translocation into the nucleus and possibly activates NF-KB, a pathway strongly associated to cancer progression." (PMID 35794863, 2022). "Previous research has implicated UBAP2L in drug resistance across various cancer types." (PMID 41029457, 2025). "UBAP2L (also known as NICE-4) has been associated with various cancer types, but the cellular mechanisms underlying its oncogenic potential remain unknown." (PMID 38652117, 2024). "Recent studies showed that UBAP2L is associated with cancer cell proliferation." (PMID 37059803, 2023). "Understanding this balance requires further exploration of how SG dynamics mediated by UBAP2L’s post-translational modifications influence drug responses across various cancer subtypes." (PMID 41029457, 2025). "A central finding of our work is the involvement of UBAP2L in orchestrating stress granule (SG) formation, a critical adaptive response that enables cancer cells to survive therapeutic stress." (PMID 41029457, 2025). "UBAP2L is upregulated in several cancer tissues and its depletion has been shown to inhibit cancer cell proliferation." (PMID 39007803, 2024). "Recent work has demonstrated that UBAP2L is overexpressed in a variety of cancers and as such it has gained significant attention of researchers over the past years." (PMID 35794863, 2022). "Complementary studies verified these conclusions in vivo where inhibition of UBAP2L led to defective cancer invasion in xenografts." (PMID 35794863, 2022). "Recent studies have illustrated that UBAP2L participates in the growth and metastasis of various types of cancers, such as prostate cancer, colorectal carcinoma, hepatocellular carcinoma, glioma, lung adenocarcinoma, and breast carcinoma." (PMID 35304439, 2022). "Consistently, cells lacking UBAP2L harbor increased epithelial (E-cadherin, CK-18) and decreased mesenchymal markers (N-cadherin, vimentin), highlighting UBAP2L’s crucial role in regulating the metastatic potential of cancer cells." (PMID 35794863, 2022). "These include a role for UBAP2L overexpression in various types of cancer and in pathologies that are related to protein aggregation in neurodegeneration." (PMID 34807903, 2021). "Furthermore, we utilized the CancerSEA dataset (cancer single-cell state atlas) to explore the role of UBAP2L in various types of malignant tumors." (PMID 41029457, 2025). "In nearly all cited cancer studies, UBAP2L is suggested to act as an oncogene promoting cancer cell proliferation and growth in vitro and in vivo, thus providing an explanation to the existing negative correlation between UBAP2L expression and patients’ prognosis." (PMID 35794863, 2022). "Of particular interest, the PI3K/Akt pathway is implicated in a broad range of cellular processes including cell proliferation but also apoptosis, angiogenesis, replicative immortality, invasion and metastasis, pointing out to UBAP2L oncogene as a golden target for future anti-cancer therapies." (PMID 35794863, 2022). "In addition, UBAP2L has recently emerged as a master regulator of growth and proliferation in several human cancers, where it is suggested to display oncogenic properties." (PMID 35794863, 2022). "However, further efforts are required in order to dissect how UBAP2L precisely regulates signaling pathways to enable cancer progression." (PMID 35794863, 2022). "Moreover, UBAP2L is overexpressed in different types of cancer, displaying oncogenic potential and often correlating with poor prognosis." (PMID 35794863, 2022). "Intriguingly, UBAP2L seems to be involved in the regulation of several hallmarks of cancer." (PMID 35794863, 2022).
cancer (continued). "Our review aimed at highlighting the growing evidence on the oncogenic potential of UBAP2L that may identify UBAP2L as a promising target and stimulate research on UBAP2L-based future cancer therapies." (PMID 35794863, 2022). "UBAP2L has oncogenic properties in various cancers, but in the liver, its role is poorly defined and UBAP2L was never associated to SG formation." (PMID 34502337, 2021). "UBAP2L has been reported to be overexpressed in multiple cancers, and knockdown of UBAP2L could suppress malignant behaviors of cancer cells." (PMID 34823423, 2021).
tumor (10 papers, 2016 to 2025). "Subsequently, we constructed an in vivo tumor model to evaluate the effects of the UBAP2L S305A mutant." (PMID 41029457, 2025). "Clinically, UBAP2L overexpression correlates with advanced tumor phenotypes and poor prognosis in multiple carcinomas." (PMID 41029457, 2025). "Following sunitinib treatment, the UBAP2L S305A mutant group showed slower tumor growth, smaller tumor size, and lower tumor weight." (PMID 41029457, 2025). "The apoptotic marker (cleaved caspase 3) and proliferation marker (Ki67 and PCNA) staining ascertained that UBAP2L knockdown enhance the anti-tumor activity of sunitinib in vivo through the inhibition of proliferation and the promotion of apoptosis." (PMID 41029457, 2025). "Conversely, UBAP2L-WT overexpression markedly enhanced tumor growth and weight after sunitinib treatment." (PMID 41029457, 2025). "Our data provide evidence that PCK1 overexpression can inhibit tumor cell growth via down-regulation of UBAP2L Ser 454 phosphorylation and increasing autophagy, and that low PCK1 expression is an independent predictive factor for CRC recurrence and metastasis." (PMID 37062825, 2023). "IHC analysis showed PCK1 and ATG5 was up-regulated, while P62 and p-UBAP2L Ser454 expression was down- regulated in PCK1-OE tumor tissues." (PMID 37062825, 2023). "This decrease in tumor burden corresponded with a >25% reduction in RPL31 staining of tumor sections, further substantiating a role for UBAP2L in regulating translation in vivo in PDAC." (PMID 37673892, 2023). "Mechanistically, we demonstrate that Prmt1 affects tumor growth primarily by regulating de novo protein translation though Ubap2l’s control of rRNA and ribosomal proteins." (PMID 37673892, 2023). "Ubap2l KO led to a >75% reduction in tumor burden when these cells were orthotopically transplanted into the pancreas of syngeneic mice." (PMID 37673892, 2023). "As a protein of the ubiquitin—proteasome pathway system, UBAP2L is found in high-density cell fractions containing ubiquitin, and is involved in various tumor-related processes." (PMID 37062825, 2023). "Aberrant overexpression of UBAP2L has been shown to be involved in tumor growth and metastasis and predicts poor survival prognoses." (PMID 35304439, 2022). "UBAP2L promotes tumor growth and metastasis, and patients with high expression of UBAP2L have unfavorable prognoses." (PMID 34900444, 2021). "The tumor-suppressing effect of UBAP2L silencing was abolished by forced activation of β-cateninS33A." (PMID 34823423, 2021). "In particular, UBAP2L was markedly and highly expressed in T2 tumours (72.5 % vs. 27.5 %) and LCAT was lowly expressed in T2 tumours (30.0 % vs. 70.0 %) and highly expressed in T1 tumours (72.6 % vs. 27.4 %)." (PMID 27567667, 2016). "Such duality implies context-dependent roles in therapy resistance, where stress-induced SG formation may transiently protect tumor cells from cytotoxic agents, while constitutive UBAP2L activity drives proliferative signaling." (PMID 41029457, 2025). "Notably, sunitinib combined with UBAP2L knockdown impressively mitigated tumor growth compared with the control group, whereas UBAP2L knockdown or sunitinib alone exhibited a partial inhibitory effect." (PMID 41029457, 2025). "Tumor volume (654 ± 24.3 vs. 169 ± 19.5 mm3, P = 0.001) and weight (0.6 ± 0.08 vs. 0.36 ± 0.02 g, P = 0.025) were notably increased in the p-UBAP2L at Ser454 (A) group compared with the p-UBAP2L at Ser454 ctrl group (P < 0.01)." (PMID 37062825, 2023). "This suggests that UBAP2L plays an important role in tumor metastasis." (PMID 35304439, 2022). "The anti-tumor effect of miR-148b-3p was partly reversed by UBAP2L overexpression." (PMID 34823423, 2021). "In addition, UBAP2L was confirmed to be a target of miR-148b-3p, and the tumor-suppressing effect of miR-148b-3p was antagonized by UBAP2L." (PMID 34823423, 2021). "The tumor-suppressing effect of the UBAP2L knockdown was abolished by β-catenin activation." (PMID 34823423, 2021).
tumor (continued). "Furthermore, the role of stress granules in promoting tumor drug resistance may involve a dual mechanism, necessitating further investigation into the potential interactions between UBAP2L and stress granules." (PMID 41029457, 2025). "Our interrogation of publicly available scRNA-seq data revealed that UBAP2L is upregulated in PDAC cells compared to normal ducts and that its expression increases with tumor stage." (PMID 37673892, 2023). "This hypothetical functional complex consisting of BAG3, HYOU1, GRB2, UBAP2L and DNAJB4 could be very important in PDAC since, in addition to BAG3, interactors also play an important role in tumor pathology." (PMID 35406724, 2022). "Also, previous studies showed UBAP2L was amplified in LUAD and is critical for tumor metastasis." (PMID 35433677, 2022).
neurodevelopmental disorder (2 papers, 2022 to 2024). A behavioral and cognitive disorder with onset during the developmental period that involves impaired or aberrant development of intellectual, motor, or social functions. "UBAP2L-deficiency syndrome, also known as neurodevelopmental disorder with impaired language, behavioral abnormalities, and dysmorphic facies (NEDLBF, OMIM 620494), is an extremely rare autosomal dominant disorder." (PMID 39720179, 2024). "In this report, we identified a novel heterozygous frameshift variant (c.2453_2454del (p.Tyr818Trpfs*3)) in the UBAP2L gene of a patient with a neurodevelopmental disorder (NDD)." (PMID 39720179, 2024). "UBAP2L-deficiency syndrome, also known as neurodevelopmental disorder with impaired language, behavioral abnormalities, and dysmorphic facies (NEDLBF, OMIM 620494), is caused by heterozygous loss-of-function variants in the UBAP2L gene, located at 1q21.3." (PMID 39720179, 2024). "There are multiple potential mechanisms by which UBAP2L may influence neurodevelopmental disorders." (PMID 39720179, 2024).
genetic diseases (1 paper, 2026). "There are no reports to show the steady or inducible decrease of UBAP2L expression except for specific genetic diseases." (PMID 41542566, 2026).
infection (1 paper, 2024). The state of being infected such as from the introduction of a foreign agent such as serum, vaccine, antigenic substance or organism. "Collectively, our results show that NSP3 blocks the UBAP2L-FMRP interaction necessary for association of FMRPs with stress granules and this could act to antagonize antiviral defense mechanisms efficiently during early stages of infection." (PMID 38177924, 2024). "Since UBAP2L plays an important role in nucleating stress granules, we speculated that NSP3 affected the ability of FXR1 to associate with these structures through competition during infection." (PMID 38177924, 2024).
UBAP2L also shares sentences with these, for which no sentence is quoted: cervical carcinoma (2 papers); Anxiety (1); breast tumors (1); colon cancer (1); developmental delay (1); hematological malignancies (1); invasive breast carcinoma (1); lung adenocarcinoma (1); Motor delay (1); ovarian carcinoma (1); Seizure (1); speech delay (1).